TOM1L2 (target of myb1 like 2 membrane trafficking protein)
Description:
Acts as a MYO6/Myosin VI adapter protein that targets myosin VI to endocytic structures. May also play a role in recruiting clathrin to endosomes. May regulate growth factor-induced mitogenic signaling.
Tractability: PROTAC: ubiquitination databases record sites on it; its protein half-life has been measured.
Gene: Protein-coding gene on chromosome 17 (17,843,507 to 17,972,469, reverse strand). Ensembl gene ENSG00000175662.
Subcellular location (Human Protein Atlas): Basal body; Microtubules; Primary cilium; Vesicles
Gene Ontology:
Molecular function: clathrin binding; protein binding; protein kinase binding; phosphatidylinositol binding; ubiquitin binding
Biological process: negative regulation of mitotic nuclear division; signal transduction
Cellular component: extracellular exosome; endosome; membrane
Genetic constraint (gnomAD): Loss-of-function variants: 31 observed, 68.18 expected, observed/expected ratio (o/e) 0.45, 90% interval 0.34 to 0.61. The upper end of that interval is the gene's LOEUF score, 0.61, which puts it in group 2 of 6, group 1 being the genes least tolerant of losing a copy. Missense variants: 606 observed, 683.79 expected, observed/expected ratio (o/e) 0.89, 90% interval 0.83 to 0.95. Synonymous variants: 256 observed, 261.53 expected, observed/expected ratio (o/e) 0.98, 90% interval 0.88 to 1.09.
Homologues: Orthologues: chimpanzee TOM1L2 (99% identical), macaque TOM1L2 (99% identical), guinea pig TOM1L2 (96% identical), rat Tom1l2 (95% identical), mouse Tom1l2 (95% identical), dog TOM1L2 (90% identical), pig TOM1L2 (89% identical), tropical clawed frog tom1l2 (81% identical), rabbit TOM1L2 (78% identical), zebrafish TOM1L2 (72% identical), Drosophila melanogaster Gga (21% identical), Drosophila melanogaster Stam (17% identical), and 3 more. Paralogues in human: TOM1 (62% identical), TOM1L1 (31% identical), GGA3 (27% identical), GGA1 (27% identical), HGS (23% identical), STAM (23% identical), GGA2 (22% identical), STAM2 (21% identical), WDFY1 (12% identical), WDFY2 (12% identical).
Diseases named in the same sentence as TOM1L2 in open-access papers:
TOM1L2 is named in the same sentence as 28 diseases in open-access papers, as found by Europe PMC text mining. Sharing a sentence is not in itself a finding about the gene and the disease. The quoted sentences say what the papers report.
osteosarcoma (3 papers, 2012 to 2023). A usually aggressive malignant bone-forming mesenchymal neoplasm, predominantly affecting adolescents and young adults. "For example, both fusion partners of the COPS3-TOM1L2 fusion transcript have been described to be frequently amplified in osteosarcoma, and TOM1L2 is involved in a recurrently detected rearrangement (TOM1L2-BRAF) in myxoinflammatory fibroblastic sarcomas." (PMID 36232302, 2022).
Hepatic steatosis (1 paper, 2024). Steatosis is a term used to denote lipid accumulation within hepatocytes. "We identified 98 and 119 genes that were significantly positively and negatively correlated with hepatic steatosis, respectively, after FDR correction (Padj < 0.05, FDR correction), including trans-eGenes PEMT and TOM1L2." (PMID 38837944, 2024).
myopia (1 paper, 2024). "Eight pairs (protein-coding genes TOM1L2, MXRA7, RHPN2, and HINT1 for senile cataract, WARS1 and TDRD7 for AMD, STAT6 for myopia, and TPPP3 for DR) are newly reported in this study." (PMID 39408566, 2024).
pulmonary disease (1 paper, 2023). "We detected two previously unreported variants, one in TOM1L2 and one in TDP1, in multiple patients with pulmonary disease." (PMID 36769106, 2023).
pulmonary fibrosis (1 paper, 2023). Chronic progressive interstitial lung disorder characterized by the replacement of the lung tissue by connective tissue, leading to progressive dyspnea, respiratory failure, or right heart failure. "Keeping in mind the significance of the AT2 cells in pulmonary fibrosis, it is interesting to speculate on a role for TOM1L2 in these cells." (PMID 36769106, 2023).
Smith-Magenis syndrome (1 paper, 2021). Smith-Magenis syndrome (SMS) is a complex genetic disorder characterized by variable intellectual deficit, sleep disturbance, craniofacial and skeletal anomalies, psychiatric disorders, and speech and motor delay. "These include a region located within the MHC, another located on chromosome 17 containing DLG2, TOM1L2, and overlapping the Smith-Magenis syndrome deletion, and another on chromosome 16 containing CENPT and PRMT7." (PMID 33646943, 2021).
Splenomegaly (1 paper, 2023). Abnormal increased size of the spleen. "In mice expressing low levels of TOM1L2, an abnormal immune response was observed which was characterized by increased incidence of skin and eye infections, splenomegaly, and tumors." (PMID 36769106, 2023).
Stroke (1 paper, 2024). Sudden impairment of blood flow to a part of the brain due to occlusion or rupture of an artery to the brain. "For ACD‐stroke, we identified 56 variants mapping to 10 genes on chromosomes 17, 8, 11, 15, 4, and 12, most of which are located at the SREBF1/TOM1L2 locus (p < 1e‐10) on chr17." (PMID 39046104, 2024).
cancer (3 papers, 2019 to 2022). A tumor composed of atypical neoplastic, often pleomorphic cells that invade other tissues. "In addition, we sought to test the differential expression of RAI1 and TOM1L2 genes that were also located in the ±25 kb flanking region of this CpG and had valid gene expression information in both cancer datasets." (PMID 35710732, 2022).
tumor (2 papers, 2012 to 2017). "The hazard ratios of LCLAT1 and CCDC43 are positive, indicating the anti- survival function of these genes, while the coefficients of other 5 genes are negative, including ENSG00000269386 (RAB11B-AS1), TOM1L2, AMPD3, MINK1 and WDTC1, indicating that they may be tumor suppressor genes." (PMID 28331188, 2017).
TOM1L2 also shares sentences with these, for which no sentence is quoted: Parkinson disease (2 papers); Alzheimer disease (1); atherosclerosis (1); cardiovascular diseases (1); cervical adenocarcinoma (1); cervical cancer (1); cervical squamous cell carcinoma (1); colorectal cancer (1); dementia (1); Huntington disease (1); inflammatory bowel disease (1); leprosy (1); metabolic syndrome (1); neurodegenerative disease (1); rheumatoid arthritis (1); senile cataract (1); type 1 diabetes (1); type 2 diabetes (1).